CD4 (CD4 molecule)
Diseases named in the same sentence as CD4 in open-access papers (continued):
Sharing a sentence is not in itself a finding about the gene and the disease.
HIV-1 infection (continued). "It has been reported that HIV-1 infection could activate immune responses and the continuous immune activation results in rapid differentiation of a subset of CD4+ and CD8+ T cells and activation-induced cell death (33, –, 35), which may cause elimination of HIV-1 reservoir." (PMID 35727067, 2022). "Furthermore, CRISPR-edited ISG15ko primary CD4+ T cells were less susceptible to HIV-1 infection compared to cells treated with non-targeting controls." (PMID 35333911, 2022). "During early HIV-1 infection, the transmigration of infected monocytes and CD4+ cells across the blood–brain barrier leads to the infection of cells, including microglia, in the central nervous system; microglia are also a long-term viral reservoir for productive HIV-1 infection." (PMID 36012364, 2022). "Based on the functional importance of CD4 and CXCR4 receptors for HSPC transduction, we investigated the frequency of CD4/CXCR4 and CD4/CCR5 double-positive cells in cord blood and bone marrow HSPC subsets from nine donors to define subpopulations potentially susceptible to HIV-1 infection." (PMID 36230931, 2022). "Since the selenoproteome of primary CD4 T-cells isolated from healthy donors seemed well responsive to selenium level variations and different from Jurkat cells’ selenoproteome, we also investigated whether selenium modified HIV-1 infection in this model." (PMID 35163318, 2022). "Thus, it is necessary to further study whether increased CD4+ and CD8+ Effector-GNLY cells are associated with microbial translocation and microbiota disturbance due to gut mucosal injury induced by chronic HIV-1 infection." (PMID 35351857, 2022). "However, for a long time, it remained unclear whether necroptosis was induced in CD4+ T cells following HIV-1 infection in vivo until we showed it in CB-HSC-NOJ mice." (PMID 33924786, 2021). "Thus, the increased activation of platelets and CD4+ T cells could partially explain the elevated formation of platelet-CD4+ T cell aggregates during HIV-1 infection." (PMID 34987521, 2021). "We hypothesized that through phagocytosis of T/F virus-infected CD4+ T cells, macrophages could become infected with these viruses, a process that would potentially initiate interhost viral dissemination at early stages of HIV-1 infection." (PMID 34425695, 2021). "In acute HIV-1 infection, these cells might partake in the complex set of immune responses and activation, contributing to the viral set-point, through their ability to activate CD4+ T cells, the primary targets of HIV-1 infection." (PMID 34578386, 2021). "Direct evidence of this was observed in CSF during acute HIV-1 infection in our study through elevated pro-inflammatory chemoattractants IL-10, IP-10, neopterin, and sCD163, consistent with prior reports, and correlation between IP-10 concentration and activated CD4+ and CD8+ T cells and monocytes." (PMID 34874976, 2021). "Several independent studies have also reported productive HIV-1 infection of submucosal DCs, with active replication prior to transmission to other cells (termed cis-infection), although productive infection of DCs compared to CD4+ T-cells is 10- to 100-fold lower." (PMID 33669846, 2021). "Recovery of CD4 lymphocytes occurs in the first 2 years after starting ART and is associated with age and the pre-existing degree of HIV-1-related immunodeficiency, so long-term exposure to HIV-1 infection damages the immune system in ways that are difficult to correct due to exhaustion." (PMID 34504234, 2021). "We were interested in determining whether GPI-anchored m36.4 can produce selective survival and expansion advantages in transduced human CD4+ T cells compared to unmodified cells during HIV-1 infection, which is a key point as a potential gene therapy approach." (PMID 33462383, 2021).
HIV-1 infection (continued). "However, it remains unknown how iNKT cells respond during acute HIV-1 infection (AHI), a period which is associated with inflammation, damage to the gastrointestinal (GI) tract, and the loss of memory CD4+ T cells." (PMID 34753817, 2021). "Therefore, an understanding on how this subset of CD4+ T cells becomes infected could provide important clues in the development of strategies to thwart the early establishment of HIV-1 infection." (PMID 33688006, 2021). "Soluble CD4 (sCD4), which targets the CD4-binding site (CD4bs), could inhibit HIV-1 infection." (PMID 33807292, 2021). "Attention will need to shift to further investigate myeloid reservoirs as literature over the past few decades has shown macrophages are not only susceptible to HIV-1 infection but also assist in sustaining viral persistence, even when CD4+ T cells are not present." (PMID 33897659, 2021). "We next tested whether these MxB mutants inhibit HIV-1 infection of CD4+ T cells." (PMID 34093497, 2021). "Thus, TB-specific CD4+ T cells are preferentially infected and depleted by HIV-1 infection." (PMID 31910871, 2020). "Finally, given that the HIV-1 subtypes examined in our study are reported to display differential in vivo pathogenicity, we wanted to explore relationships between Vpu function and clinical parameters of HIV-1 infection, namely, CD4 count and plasma viral load (pVL)." (PMID 32376625, 2020). "However, no studies have directly compared different target cell (resting CD4+ T cells, activated CD4+ T cells, or macrophages) lncRNA expression profiles upon HIV-1 infection at different time points and determined whether there are unique lncRNA signatures." (PMID 32183241, 2020). "However, the dynamics of the CD161+ CD4+ T cell population during acute HIV-1 infection remains unknown." (PMID 33322496, 2020). "Thus, CMV-specific CD4+ T cells remains relatively functional during HIV-1 infection." (PMID 31910871, 2020). "Indeed, macrophages and DCs present in PBMCs from MAVS minor donors may exert a DDX3-induced MAVS-mediated type I IFN response upon in vitro HIV-1 infection, which can interfere with virus replication in the CD4+ T cells." (PMID 32708557, 2020). "However, HIV-1 infection is not solely restricted to CD4+ T cells, and other cell types are also susceptible to the virus." (PMID 32576602, 2020). "We found that EBV, which transforms B cells, renders them susceptible to HIV-1 infection in a CXCR4 and CD4-dependent manner in vitro and that CXCR4-tropic HIV-1 integrates into the genome of these B cells with the same molecular profile as in autologous CD4+ T cells." (PMID 32576602, 2020). "Importantly, T7E1 assay of the CCR5 gene in CD4+ T cells from the spleens showed the mutation in CCR5-modified CD4+ T cells with or without HIV-1 infection, which was indicative of successful modification and engraftment of CD4+ T cells in humanized mice." (PMID 31186067, 2019). "Interestingly, transcript levels of both MALAT1 and NEAT1 have been shown to be upregulated in PBMCs of HIV-1-infected patients, and, notably, expression of NEAT1 correlated with CD4+ T cell counts, indicating potential function of these lncRNA during HIV-1 infection." (PMID 31336952, 2019). "Thus, we hypothesized that arginase-2 activity by CECs may enhance HIV-1 infection/replication in CD4+ T cells." (PMID 31772057, 2019). "The much slower CD4 T-cell decline is in line with a preserved thymic function but contrasts with the in vitro cytopathogenicity and a relationship between CD4 T-cell depletion and immune activation that appears to be similar to that observed during HIV-1 infection." (PMID 31095640, 2019). "Furthermore, the presence of low molecular weight Apolipoprotein B mRNA editing enzyme 3G (APOBEC3G) in naïve CD4+ T-cells has been demonstrated to inhibit reverse transcription and HIV-1 infection of primary T-cells, coupled with limited availability of nucleotides in quiescent CD4+ T-cells." (PMID 31487807, 2019).
HIV-1 infection (continued). "The enhancing effect of ISH on anti-Env antibody levels was not attended with increased Env-specific IFN-γ CD4 T-cell responses that otherwise may potentially influence the susceptibility to HIV-1 infection." (PMID 31569763, 2019). "HIV-1 infection triggers massive depletion of CD4 T cells, and it was first proposed that the increased risk to develop TB upon HIV infection might by associated with the severe reduction of CD4 T-cell numbers." (PMID 30541853, 2019). "Additionally, this protocol could be modified to study HIV-1 infection of other cells including CD4+ T cells." (PMID 32002449, 2019). "Therefore, although HIV-1 and HIV-2 infections appear to follow the same basic pathogenic mechanisms, during natural HIV-2 infection, the lower viral production, lower CD4 T-cell decline and slower progression to disease indicate a more favorable host-pathogen balance than during in HIV-1 infection." (PMID 31095640, 2019). "Indeed CCR5 expression followed here-in the same progressive gradient of expression among memory CD4 T-cells, with a slightly lower expression on TCM than on TTM, as observed during HIV-1 infection while the CCR5 expression normally increased on activated CD4 T-cells from HIV-2 infected individuals." (PMID 31095640, 2019). "Moreover, regardless of the route of HIV-1 infection, a massive loss of CD4+ memory T-lymphocytes in the GALT is observed within the first few weeks of infection." (PMID 31487324, 2019). "Thus, augmented CD38 expression induced by calcitriol might have a role in reducing HIV-1 infection of CD4+ T cells." (PMID 31550271, 2019). "Moreover, some evidence supports the theory that HIV-1 can establish latent infection in actively replicating CD4+ T cells, suggesting that HIV-1 infection of both resting and activated primary CD4+ T cells could result in latency." (PMID 32038533, 2019). "Having demonstrated that CD161+ CD4+ T cells are highly permissive to HIV-1 infection, we went on to further investigate whether these cells have the potential to survive longer and proliferate in vitro, which is a critical prerequisite for promoting the clonal expansion of latent HIV-1." (PMID 31594817, 2019). "Therefore, we identified CD4+ ILC1s as a new target for HIV-1 infection." (PMID 29304123, 2018). "Here, we showed that in acute HIV-1 infection, the frequency of ki67 in CD4+ T cells correlated with the expression of phenotypic activation markers, and more importantly, it inversely correlated with CD4+ T cell decline in patients with acute infection over time." (PMID 29636753, 2018). "While the observed loss of CD4+ T cell-associated HIV-1 DNA and RNA from the individual who received multiple cycles of brentuximab vedotin is only anecdotal, this case finding inspired the detailed ex vivo work of CD30 as a potential marker for HIV-1 infection." (PMID 29470552, 2018). "In fact, a recent study showed that SIV Vpx of red-capped mangabeys and mandrills (SIVrcm/mnd-2) enhances HIV-1 infection specifically in resting CD4+ T cells in a SAMHD1- and dNTP pool-independent manner and led the authors to suggest the existence of an unknown restriction factor." (PMID 29764952, 2018). "In addition to the death of infected cells, the dramatic reduction in total CD4+ T cell counts observed in HIV-1 infection is considered mainly due to apoptotic and bystander cell death and possibly killing of CD4+ T cells following abortive infection with HIV via pyroptosis." (PMID 28264054, 2017). "Thus, HIV-1 infection may have enhanced the antibacterial properties of microbe-exposed LP CD4+ T cells." (PMID 28241075, 2017). "Thus, astrocytes, long proposed to undergo an atypical HIV-1 infection in the brain but which lack the primary HIV-1 receptor CD4, are phagocytic and engulf dying HIV-1-infected cells leading to markers of viral infection but are resistant to viral entry and infection." (PMID 29312342, 2017).
HIV-1 infection (continued). "Both CD4+ T central and effector cells have been associated with virus control in HIV controllers whilst memory CD8+ T cells have also been associated with low viral set points in early HIV-1 infection, indicating the importance of vaccine-generated memory T cells." (PMID 28069361, 2017). "Therefore, we hypothesized that HIV-1 infection induced CD4+ T-cell activation and augmented A3H expression in humanized mice, and this resulted in robust anti-viral effect by endogenous A3H." (PMID 28475648, 2017). "Second, shRNA-mediated depletion of SUN2 in human primary CD4+ T cells decreased permissivity to HIV-1 infection and the inhibition of CypA function only had a minor effect in SUN2-depleted cells, while in control cells CypA inhibition caused a significantly greater reduction in HIV-1 infection." (PMID 28747499, 2017). "Furthermore, it appears that the role of autophagy in HIV-1 infection is very closely related to the cell type, given that the early steps of autophagy are required for viral replication in macrophages, but are detrimental in CD4+ T cells." (PMID 28946621, 2017). "Furthermore, to explore the effect of disruption of both co-receptors on the protection against a dual-tropic HIV-1 variant instead of a distinct co-receptor tropism virus, we performed the HIV-1 infection assay by treating the edited CD4+ T cells with HIV-1NL4-3 and HIV-1YU-2 (1:1) simultaneously." (PMID 28904745, 2017). "Thus, following exposure to HIV-1 infection the constitutive HSP70 in HIV virions may boost CD4+ TSCM, CC chemokines and A3G mediated inhibition of HIV-1 or SIV replication." (PMID 28432326, 2017). "We then examined whether HIV-1 infection affects the level of let-7i in CD4+ T cells." (PMID 27145859, 2016). "As might be expected from the effects of HIV-1 infection on Mtb-reactive CD4 T cell populations, modular analysis showed reduced abundance of T cell associated transcripts in the TST, but other selected cell type and pre-defined stimulus-specific modules were comparable in the two groups." (PMID 26986567, 2016). "Nuclear coexistence between PKCθ and Tat during acute HIV-1 infection could be used as a therapeutic target because selective PKCθ inhibitors could disrupt this association and avoid the massive HIV-1 replication and CD4 depletion that occur during the first stages of the illness." (PMID 26973648, 2016). "Thus, our results clarify how AAT inhibits HIV-1 infection in primary CD4+ T cells." (PMID 27473095, 2016). "Likewise, in this study we showed that HIV-1 infection suppresses IL-2 through let-7i, which greatly impaired the protective effect against viral infection- and activation-induced apoptosis of the peripheral blood CD4+ T cells by IL-2." (PMID 27145859, 2016). "The DN T cells may compensate for the CD4+ T cells, therefore, poor restoration of these DN T cells in INRs may result in impaired immune responses during HIV-1 infection and thus accelerate the disease progression among these patients despite the fact that they have similar CD4+ T cell counts." (PMID 28018346, 2016). "Besides the CD4-positive T-cell population, macrophages are thought to be important in the persistence and pathogenesis of HIV-1 infection due to their widespread presence in various tissues and their contribution to long-lived reservoirs of virus-infected cells." (PMID 27068393, 2016). "Our data show that HIV-1 infection could decrease the IL-2 expression of CD4+ T cells in vitro." (PMID 27145859, 2016). "Restoration of protective Ab responses by CD4+ T cell immunotherapy under the conditions examined advocates the consideration of similar approaches in other chronic infections, particularly when CD4+ T cell help is known to be defective, such as in HIV-1 infection." (PMID 27647833, 2016).
HIV-1 infection (continued). "However, others have found that although p21 expression was higher in CD4+ T cells from HIV controllers than from healthy controls, it did not correlate with CD4+ T-cell susceptibility to HIV-1 infection." (PMID 25746435, 2015). "The distribution of human CD4+, CD8+ T cells, and B cells reconstituted in humanized DRAG mice is similar to that reported in humans, suggesting that the DRAG mice might be susceptible to HIV-1 infection." (PMID 26034905, 2015). "As isolated Vδ2 cells can be infected in vitro we hypothesize that the activated immune environment during untreated HIV infection induces transient CD4 upregulation, rendering Vδ2 cells permissive for HIV-1 infection, and founding a substantial population of latently infected γδ cells." (PMID 26473478, 2015). "Therefore, sCD4 and small molecules that mimic the host cell CD4 receptor may inhibit HIV-1 infection either by preventing attachment to CD4 on the cell surface or by inducing a short-lived activated state." (PMID 24489681, 2014). "In untreated subjects with chronic HIV-1 infection and active HIV replication (i.e. detectable viral loads), percentages of Tim-3+ bulk (p = 0.006, Spearman r = 0.46) and CD56dim (p = 0.004, Spearman r = 0.48) NK cells were even more strongly associated with CD4+ T-cell counts." (PMID 23866914, 2013). "Therefore, we infected CD4+ T cells and myeloid-lineage cells from CD4/R5/cT1 mice and humans with NL-LucR.T2A-BaL.ecto and compared their relative capacity to support productive in vitro HIV-1 infection." (PMID 23691059, 2013). "Furthermore, we demonstrated inhibition of HIV-1 infection in resting CD4+ T-cells." (PMID 23294842, 2013). "However, T cell co-stimulation may also lead to increased HIV co-receptor expression and activation of other transcription factors such as NF-ATc that could provide additional pathways for up-regulation of HIV-1 infection in CD4+ T cells interacting with PIM6." (PMID 24282561, 2013). "The binding of HIV virions to these cells and their transfer to CD4+ cells may be an important step in the establishment of mucosal HIV-1 infection, especially in the setting of postnatal transmission, as carbohydrates in milk may compete for interaction with lectin-binding molecules on DCs." (PMID 23305422, 2013). "However, the initial event necessary to initiate HIV-1 infection remains the binding of Env to CD4." (PMID 23514633, 2013). "We further examined whether HIV-1 infection of human primary CD4+ T cells was dependent on ADAP." (PMID 24047317, 2013). "Similarly, Vpx from HIV-2 or SIVsm degrades SAMHD1 in resting CD4+ T-cells and efficiently increases single-cycle and replication-competent HIV-1 infection, which is correlated with increased products of full-length viral cDNA and 2-LTR circles in infected cells." (PMID 23092163, 2012). "While this is not the only Cdk9 residue to be phosphorylated, it certainly is critical for P-TEFb function, and it is likely that low levels of Thr186-phosphorylated Cdk9 may contribute to the refractoriness of resting CD4+ T cells and monocytes to HIV-1 infection and replication." (PMID 24832049, 2012). "One potential explanation may be that the subpopulation of CD4+ T cells expressing TNF-α and CTLA-4 or PD-1 may be less readily able to support productive HIV-1 infection despite evidence that CTLA-4 signaling may be associated with increased CCR5 expression and enhanced susceptibility to infection." (PMID 22479542, 2012). "Treatment of CD4+ T cells with Virus-Like Particles (VLP) containing Vpx results in the loss of SAMHD1 expression that correlates with an increased permissiveness to HIV-1 infection and accumulation of reverse transcribed viral DNA without promoting transcription from the viral LTR." (PMID 23092122, 2012). "Moreover, monocytes and resting CD4+ T cells from AGS patients that do not express functional SAMHD1 proteins were more susceptible to HIV-1 infection." (PMID 23254112, 2012).